XAGE1B (X antigen family member 1B)
Synonyms: XAGE-1; CT12.1; GAGED2; XAGE1; XAGE1C; XAGE1D; XAGE1E; CT12.1b; CT12.1c; CT12.1d; CT12.1E; CTP9
Gene: Protein-coding gene on chromosome X (52,512,077 to 52,520,803, reverse strand). Ensembl gene ENSG00000204382.
Subcellular location (Human Protein Atlas): Nucleoplasm
Gene Ontology:
Molecular function: protein binding
Homologues: Paralogues in human: XAGE1A (100% identical), XAGE2 (31% identical), XAGE5 (28% identical), PAGE3 (27% identical), XAGE3 (27% identical), PAGE4 (26% identical), GAGE1 (19% identical), GAGE12C (19% identical), GAGE12D (19% identical), GAGE12E (19% identical), GAGE12F (19% identical), GAGE12G (19% identical), and 10 more.
Diseases named in the same sentence as XAGE1B in open-access papers:
XAGE1B is named in the same sentence as 19 diseases in open-access papers, as found by Europe PMC text mining. Sharing a sentence is not in itself a finding about the gene and the disease. The quoted sentences say what the papers report.
lung adenocarcinoma (4 papers, 2013 to 2021). A carcinoma that arises from the lung and is characterized by the presence of malignant glandular epithelial cells. "One transcript variant (XAGE-1b), was identified as a dominant antigen recognized by sera from lung adenocarcinoma patients." (PMID 23625514, 2013). "Together, our findings confirm XAGE-1b immunogenicity in lung adenocarcinoma, highlighting the importance of this CTA as a promising target for immunotherapy against this tumor subtype." (PMID 26937656, 2016). "CD4 and CD8 T cell responses against XAGE-1b in lung adenocarcinoma patients, leading to the hypothesis that XAGE-1b might be considered a potential antigen for tumor immunotherapy." (PMID 35027975, 2021). "In conclusion, altogether, our results support the relevance of the XAGE-1b antigen in Caucasian patients with lung adenocarcinoma and encourage the implementation of future immunotherapies exploiting the high immunogenic of this antigen in this patients’ population." (PMID 26937656, 2016).
lung carcinoma (3 papers, 2021 to 2022). "The CD8 T-cell clone shows cytotoxicity against tumours expressing XAGE-1b and the appropriate HLA class I allele, suggesting that XAGE-1b is an ideal target for a lung cancer vaccine and therapy." (PMID 35574342, 2022). "The nuclear localization of the granular-like pattern of XAGE-1b in NCI-H1975 cells was consistent with previous immunohistochemical results in lung cancer tissues and cells." (PMID 35600379, 2022). "In short, these data suggest that XAGE-1b is a potential target for lung cancer therapy." (PMID 35574342, 2022).
prostate carcinoma (3 papers, 2011 to 2023). A carcinoma that arises from epithelial cells of the prostate gland. "XAGE-1b mRNA expression was also observed in 26% of prostate cancer specimens." (PMID 23625514, 2013).
hepatocellular carcinoma (2 papers, 2023 to 2024). A malignant tumor that arises from hepatocytes. "In patients with hepatocellular carcinoma, elevated serum XAGE-1B tends to be associated with a higher recurrence rate, and may be useful as a prognostic biomarker." (PMID 37081973, 2023). "Genome-wide screen by CRISPRa library in vivo for drivers of hepatocellular carcinoma (HCC) progression revealed that overexpression of XAGE1B, PLK4, LMO1 and MYADML2 genes promoted HCC cell proliferation and invasion, which were suppressed by their inhibition." (PMID 39696697, 2024).
squamous cell carcinoma (2 papers, 2010 to 2023). A carcinoma arising from squamous epithelial cells. "The frequent of XAGE-1b gene in adencarcinoma was much higher than that in squamous cell carcinoma." (PMID 20704819, 2010).
liver cancer (1 paper, 2021). An epithelial or non-epithelial malignant neoplasm that arises from the liver. "The expression of the CTA family XAGE-1b is significantly higher in liver cancer tissues and peripheral blood than in a non-liver cancer group." (PMID 34475991, 2021).
melanoma (1 paper, 2023). A malignant, usually aggressive tumor composed of atypical, neoplastic melanocytes. "Similarly, also in melanoma, lack of NY-ESO-1 and XAGE-1B in metastatic lymph nodes prolonged overall survival." (PMID 37081973, 2023).
metastatic tumor (1 paper, 2015). "XAGE-1b was expressed in both primary and metastatic tumor specimens." (PMID 26025564, 2015).
cancer (9 papers, 2011 to 2023). A tumor composed of atypical neoplastic, often pleomorphic cells that invade other tissues. "Genes such as human leukocyte antigen (HLA) complex genes HLA-DQA2/HLA-DQB2 encoding HLA-Class II molecules, cancer/testis (CT) antigen XAGE1B and FOLR genes, which are related to multiple cancers, were steadily upregulated in advanced stage." (PMID 33000418, 2021). "In a comparison of primary and recurrent lesions, other cancer-testis antigens (CTAs) including XAGE-1B were significantly upregulated in recurrent lesions." (PMID 37081973, 2023). "XAGE-1b is a cancer/testis antigen aberrantly expressed in pulmonary adenocarcinoma." (PMID 26025564, 2015). "Both XAGE1B and CABYR are tumor-specific antigens of the Cancer Testis Antigens (CTA), which have attracted research attention as potential mediators of cancer cell recognition." (PMID 35804987, 2022). "It is also notable that we identified over 10 cancer-related genes (including PHGDH, CCND1, IGFBP-2, XAGE1B/E, CYP4F22, RBM11, ORAOV1, MDK, UGT3A5, SSX5, FBL, NKX2) potentially overexpressed in EFT tumors." (PMID 30093970, 2018). "Similar to NY-ESO-1, XAGE-1b and SSX-2,4 are cancer/testis antigens shared among cancers of the prostate, lung, breast and others." (PMID 21504557, 2011).
tumor (6 papers, 2015 to 2023). "Of these three patients, one patient (X-14) expressed XAGE-1b in the tumor and mounted a local XAGE-1b-specific T cell response." (PMID 26025564, 2015). "Overall, we found local XAGE-1b-mediated Th1/Th2 cell immunity in two of 20 patients tested indicating that XAGE-1b acts as a genuine tumor antigen." (PMID 26025564, 2015). "XAGE-1b protein expression was detected in 43.6 % (17 of 39) of patients when at least two different parts of a resected tumor were assessed." (PMID 26025564, 2015). "In one patient (X-14) with diffuse (>50 %) XAGE-1b staining in the primary tumor, a T helper 1 (Th1) response to XAGE-1b was detected." (PMID 26025564, 2015). "In 20 patients, analysis of T cells isolated and expanded from the primary tumor and its draining lymph node demonstrated XAGE-1b-specific responses in two patients." (PMID 26025564, 2015). "Tumor-draining lymph node (LN) mononuclear cells were expanded in vitro in the presence (LN XAGE) or absence (LN neg) of exogenous XAGE-1b peptides." (PMID 26025564, 2015). "In conclusion, our study demonstrates that XAGE-1b acts as a genuine tumor antigen eliciting integrated systemic and/or tumor-infiltrating antigen-specific humoral and cellular immune responses in Caucasian patients with pulmonary adenocarcinoma." (PMID 26025564, 2015). "Moreover, our study reveals for the first time the presence of XAGE-1b-specific T cells in the primary lung tumor and the tumor-draining lymph nodes from 2 out of 20 evaluated patients." (PMID 26025564, 2015). "Hence, the frequency of XAGE-1b-overexpressing tumors can be underestimated when only assessing a single section of the tumor and most likely when a biopsy is analyzed." (PMID 26025564, 2015). "Our study for the first time provides evidence for the presence of XAGE-1b-specific T cells within adenocarcinoma tissue, which supports the concept that XAGE-1b acts as a genuine tumor antigen and, therefore, might form an attractive target for a vaccine-based approach of immunotherapy." (PMID 26025564, 2015). "In this study, XAGE-1b expression by tumor cells as well as the presence of systemic and/or local XAGE-1b-specific immunity was assessed in peripheral blood, tumor tissue and tumor-draining lymph nodes of Caucasian patients with pulmonary adenocarcinoma." (PMID 26025564, 2015). "Our data demonstrate that XAGE-1b overexpression is found in about 40 % of all tumors; however, positive tumors do not show overexpression in all randomly selected tumor fields." (PMID 26025564, 2015). "Another patient (X-20), without XAGE-1b expression in the primary tumor, showed XAGE-1b-specific T cell reactivity in its draining LN." (PMID 26025564, 2015). "However, XAGE-1b-positive tumors do not show protein overexpression in all tumor samples nor in all fields covering an area that approximates the size of a bronchial biopsy." (PMID 26025564, 2015). "In one patient (X-4), the biopsy of the primary tumor could not be retrieved, and hence, XAGE-1b status was not assessed." (PMID 26025564, 2015). "Furthermore, no data exist on the presence of XAGE-1b-specific T cells within the tumor or its draining lymph node." (PMID 26025564, 2015).
adenocarcinoma (2 papers, 2015 to 2016). A common cancer characterized by the presence of malignant glandular cells. "Altogether, our results support the relevance of the XAGE-1b antigen in Caucasians NSCLC patients with adenocarcinoma, and the implementation of future immunotherapies exploiting the high immunogenicity of the antigen in this patient population." (PMID 26937656, 2016). "Taking into account that XAGE-1b has been reported to be expressed in about 45% of adenocarcinomas (but only 7% of SCC), serological responses seem rather frequent in this group of patients, being found in about one third of them." (PMID 26937656, 2016). "XAGE-1b seropositive patients were exclusively found in the adenocarcinoma subgroup, and represented 13% of the subgroup." (PMID 26937656, 2016). "The correlation between serological responses to XAGE-1b and adenocarcinoma histological subtype reached statistical significance (Fisher’s exact test, P = 0.0176)." (PMID 26937656, 2016). "Two previous studies with Asian adenocarcinoma patients also assessed anti-XAGE-1b antibody frequency." (PMID 26025564, 2015). "XAGE-1b expression was observed in 45% of adenocarcinomas of Japanese patients." (PMID 26937656, 2016). "Therefore, removal of the potentially suppressive myeloid cell populations from the peripheral blood of adenocarcinoma patients before analysis of T cell responses might reveal a higher percentage of XAGE-1b-specific T cell responders among Caucasian patients." (PMID 26025564, 2015). "A recent study revealed the presence of XAGE-1b-specific antibodies in 10 % of all NSCLC patients and in 19 % of stage IIIb/IV adenocarcinoma patients." (PMID 26025564, 2015). "Our findings demonstrate that serological responses to XAGE-1b are largely restricted to adenocarcinomas as they are found in about 13% of them but are not detected in SCC." (PMID 26937656, 2016). "Thus, we confirmed that XAGE-1b is spontaneously immunogenic in NSCLC, mostly in adenocarcinomas, and demonstrated that this is the case not only in the Japanese population but also in Caucasians." (PMID 26937656, 2016).
XAGE1B also shares sentences with these, for which no sentence is quoted: non-small cell lung carcinoma (2 papers); bladder cancer (1); breast carcinoma (1); Ewing sarcoma (1); gastric cancer (1); multiple myeloma (1); ovarian carcinoma (1); synovial sarcoma (1).